RNU4-27P (RNA, U4 small nuclear 27, pseudogene)
Gene: Small nuclear RNA gene on chromosome 1 (36,402,721 to 36,402,859, reverse strand). Ensembl gene ENSG00000222821.
Homologues: Orthologues: chimpanzee U4 (99% identical). Paralogues in human: RNU4-42P (72% identical), RNU4-65P (58% identical), RNU4-36P (55% identical), RNU4-75P (53% identical), RNU4-53P (52% identical), RNU4-49P (50% identical), RNU4-15P (50% identical), RNU4-28P (47% identical), RNU4-40P (47% identical), RNU4-9P (47% identical), RNU4-32P (46% identical), RNU4-57P (46% identical), and 81 more.